COL1A1 (collagen type I alpha 1 chain)
Diseases named in the same sentence as COL1A1 in open-access papers (continued):
Sharing a sentence is not in itself a finding about the gene and the disease.
tumor (continued). "For example, collagens, such as COL1A1, COL1A2, COL3A1, COL5A2, COL6A1, COL6A2, and COL6A3 are thought to mediate tumor progression and are associated with a poor prognosis in BCa." (PMID 37277784, 2023). "In this study, our results showed that down-regulation of COL1A1 increased the expression of E-cadherin and Cav-1 in tumor cells and reduced the expression of α-SMA and FAP, thus improving the tumor microenvironment." (PMID 38045487, 2023). "This analysis indicated variable modulation of proline hydroxylation in type I and type III collagen chains, including a substantial cluster of hydroxyproline-containing peptides derived from COL1A1 that were up-regulated in tumour ECM." (PMID 37397358, 2023). "For diagnosing DPFS, FISH is employed with a positive criterion being the identification of a COL1A1-PDGFB fusion gene or PDGFB rearrangement in at least 10% of tumor cells." (PMID 37920823, 2023). "Estrogen activity can modulate components of the ECM in the tumor microenvironment, upregulating transcripts of COL1A1, and several matricellular proteins such as TNC, FN1, and POSTN." (PMID 37056757, 2023). "Down-regulation of COL1A1 expression can prevent the proliferation, invasion, and formation of tumor spheroids of HCC cells." (PMID 38001428, 2023). "In contrast, angiogenesis and oncogenic signaling (including Myc, E2F, and Pten) were dominant in control tumors, in which we also observed dominant expression of known tumor endothelial markers, e.g., Bgn, Col1a1 8,16." (PMID 35606362, 2022). "Nonetheless, Col1a1 was downregulated within tumor cells and oncostream dismantling was significant compared to NPD control." (PMID 35750880, 2022). "Similar to the results of IHC, qRT‐PCR and H&E staining, LOX and COL1A1 expressions and tumour infiltration increased in vivo when GBM cells (X01 cells) were co‐injected with MSLCs rather than when injected alone." (PMID 35908277, 2022). "Some well-known marker genes were used to identify cell types, such as EPCAM and KRT19 for tumor cell, COL1A1 and ACTA2 for CAF, CD3D and CD3E for T cell, and CD68 and CD14 for macrophage." (PMID 36499343, 2022). "Among the interactions involved in tumor invasion and growth, extracellular matrix interaction scores were higher between tumor stroma and post-treatment tumor (tumor stroma ligand: COL1A1, COL1A2, and COL3A1; post-treatment tumor receptor: ITGA2)." (PMID 36505794, 2022). "Age, tumor grade, and COL1A1 expression were independent prognostic factors in multivariate analysis." (PMID 35789341, 2022). "Histomorphometry of TRAP/Hematoxylin staining revealed decreased osteoblast numbers in EO771 tumor-bearing Col1a1-cre+;Tyro3flox/flox mice, whereas osteoclast numbers were not changed." (PMID 36509738, 2022). "Their results illustrate the increasing abundance and complexity of extracellular matrix proteins, among them fibrillar collagens such as COL1A1, 1A2, and 3A1, during tumor progression." (PMID 35684402, 2022). "We found that mesenchymal-related markers such as FN1, TGFBI, and COL1A1 were enriched in mixed-lineage tumor cells." (PMID 35962452, 2022). "In this work, Tumor Immune Estimation Resource database was used for detecting the expression level of COL1A1 in cancer and normal tissues, and aimed to explore the relationship between COL1A1 and tumor immune infiltration." (PMID 35789341, 2022). "The biological role of Linc00511 in LUAD tumor growth was examined in vivo in a xenograft tumor model, and its detailed interactions with miR-126-5p, miR-218-5p, and COL1A1 were further identified." (PMID 35842617, 2022). "In these preclinical animal models, the expression of Col1a1 was knocked down from the earliest stages of tumor development." (PMID 35750880, 2022). "Analysis of metaphyseal cancellous bone by μCT showed higher bone volume and trabecular thickness in EO771 tumor-bearing Col1a1-cre+;Mertkflox/flox mice in comparison to Mertkflox/flox mice after 12 days." (PMID 36509738, 2022).
tumor (continued). "In this research, we are aimed at exploring the expression level of COL1A1 and prognosis in LGG, and analyze the related mechanism of COL1A1 in tumor immune infiltration." (PMID 35789341, 2022). "Col1a1 inhibition not only inhibits tumor cell proliferation and migration but also decreased the infiltration of microglia/macrophages, endothelial cells proliferation, and perivascular mesenchymal-like cells." (PMID 35750880, 2022). "The scRNA-seq data showed that ITGA2 was mainly expressed in tumor cells, while its ligands COL1A1, COL1A2, COL8A1, FN1, and HSPG2 were expressed in fibroblasts and endothelial cells." (PMID 35719923, 2022). "We also explored relationship between COL1A1 and tumor immune cell infiltration by relevant tumor data from TIMER." (PMID 35789341, 2022). "In this cluster, we identified 148 differentially expressed genes, including a significant downregulation of Col1a1 and Col1a2 in tumours grown in Atf4Δ/Δ mice." (PMID 35654839, 2022). "Firstly, tumor cells secrete Tsp2 to induce the transformation of normal fibroblasts to TAFs, and TAFs remodel the extracellular matrix by secreting COL1A1, COL1A2, COL5A1, FN1, and VCAN." (PMID 35982904, 2022). "ITGB1 and ITGA1 were found among the key CAF receptors that mediate crosstalk between tumor cells and CAFs by interacting with COL1A1 and TNC and, thereby, modulating the TME." (PMID 36003785, 2022). "Previous studies have shown that the expression of COL1A1 is correlated to a variety of tumor types, and COL1A1 is highly expressed in tumor tissues and cells." (PMID 35789341, 2022). "Analysis of metaphyseal cancellous bone by μCT showed decreased bone volume and trabecular number in EO771 tumor-bearing Col1a1-cre+;Tyro3flox/flox mice in comparison to Tyro3flox/flox mice after 12 days." (PMID 36509738, 2022). "Another aspect of this study was to estimate the relevance between the COL1A1 and tumor immune infiltration, especially in LGG." (PMID 35789341, 2022). "Myofibroblasts and pericytes (stained with αSMA and COL1A1 antibodies, respectively) were evenly distributed throughout the tumor tissue, including the tumor gland and distal stroma area." (PMID 34976204, 2022). "The relativity between the expression of COL1A1 and the tumor microenvironment was evaluated using ESTIMATE algorithm." (PMID 35789341, 2022). "To further elucidate how Linc00511 affects tumor growth in vivo, we subcutaneously injected A549 cells stably transfected with Ad-sh-NC, Ad-sh-linc00511 + Ad-NC or Ad-sh-linc00511 + Ad-COL1A1 into the right flank of nude mice to establish a xenograft model." (PMID 35842617, 2022). "The increased aggressiveness of TGF-β induced CAFs was associated with increased EMT markers (Vimentin, Snail, Slug and Twist) and altered TME (e.g. COL1A1 secretion) in the tumor cells." (PMID 35666359, 2022). "Histomorphometry of TRAP/Hematoxylin staining indicates increased osteoblast numbers in EO771 tumor-bearing Col1a1-cre+;Mertkflox/flox mice, whereas osteoclast numbers were not changed." (PMID 36509738, 2022). "The results verified that knockdown of Linc00511 inhibited tumor growth and metastasis in nude mice, while COL1A1 overexpression partially counteracted the tumor suppression mediated by Linc00511 silencing." (PMID 35842617, 2022). "The protein levels of LIMK1, p-cofilin, cofilin, p-CREB, CREB, MMP2, ITGB1, and COL1A1 in mouse tumor tissues were consistent with the metastatic potential of the tumor in mice." (PMID 34079084, 2021). "Consistently, we found that the enhanced expression of the matrix protein collagen type I alpha-1 chain (Col1a1) in tumours compared to the surrounding liver tissue was diminished after inactivation of Ccne1." (PMID 34830835, 2021). "A cluster of genes that were upregulated in the tumours, compared to normal tissues were COL1A1, COL11A1, SPP1, COMP, SFRP4 and INHBA." (PMID 34824625, 2021).
tumor (continued). "Human-specific DEspR+/Col1A1 Panc1-CSC-derived TCs in PPC tumor sections are distinguished from rat host stromal fibroblasts by cell morphology, location, and negativity for human-DEspR+ expression." (PMID 33853558, 2021). "Similar to what was seen in vitro, the xenograft tumors from mut COL1A1 cells deposited less cancer-cell-derived ColI by IHC and by WB on enriched tumor ECM." (PMID 33879793, 2021). "COL1A1, encoding the subunit of type I collagen, is the main constituent of the extracellular matrix (ECM) component in tumor microenvironment and plays critical role in cancer development and metastasis." (PMID 33969120, 2021). "EPCAM and COL1A1 were used to identify tumor epithelial cells and fibroblasts, as described in a previous study." (PMID 34771607, 2021). "The findings suggest COL1A1 played a crucial part in the prognostic of lung tumor as well as reveal the potential mechanism between COL1A1 and tumor-immune, which lay the foundation for clinical research and immune targeted therapy." (PMID 33850663, 2021). "Transfection of HAPLN1 overexpression plasmids into these cells increased protein levels but reduced COL1A1 protein, tumor growth, and cancer cell migration." (PMID 34966673, 2021). "The results indicate that COL1A1 expression has correlations with tumor purity and significant correlations with CD4+ T cells, Macrophage, Neutrophil and Dendritic cell in LUAD and LUSC." (PMID 33850663, 2021). "Recent studies have also found that COL1A1 appears to exert an oncogenic effect, which promotes tumor migration by rearranging the actin cytoskeleton and regulating the planar polarity of the cells." (PMID 34362454, 2021). "Genes in the high expression groups, namely, COL1A1, COL4A1, COL12A1, and PDGFRB, were all enriched in the MAPK and PI3K–Akt signaling pathways, which are closely associated with tumor cell proliferation, invasion, and cell cycle." (PMID 35111208, 2021). "Although COL1A1 mRNA is usually upregulated in tumor tissues, there is a small group of tumors that has downregulated mRNA expression, mainly due to promoter methylation." (PMID 34943943, 2021). "Immunohistochemistry revealed differential distribution of COL1A1 showing maximum levels in tumour tissue and gradually decreasing in distant adipose tissue." (PMID 33670920, 2021). "COL1A1 expression was distinctly correlated to tumor purity (cor = −0.257; p = 1.67e − 02), CD4+ T cells (cor = −0.221; p = 4.38e − 02), macrophages (cor = 0.414; p = 8.86e − 05), and neutrophils (cor = −0.266; p = 1.45e − 02)." (PMID 33490271, 2021). "Altogether, we showed that BMP1 depends on cancer-cell-derived COL1A1 for its function to suppress PDAC tumor growth and metastasis." (PMID 33879793, 2021). "Smad2, Smad3, Smad4, and COL1A1 proteins were strongly expressed in tumor tissues from CRC patients compared with normal colon controls." (PMID 34966673, 2021). "Among them, PANC1 cells had the highest COL1A1 expression and the largest tumor-suppressing effect by BMP1, while AsPC1 had the lowest COL1A1 expression and no BMP1 effect (see the next section for COL1A1 expression data)." (PMID 33879793, 2021). "Multiplex-IF shows that PPC-TCs in tumor cell islands co-express human-specific DEspR and Col1A1, but that DEspR−/Col1A1+ TCs are also present in the same tumor cell islands." (PMID 33853558, 2021). "COL1A1, a type I collagen, is a main component for the family of fibrillar collagen and is engaged in the tumor invasion and progression." (PMID 35111208, 2021). "Actually, Col1a1 is often increased in cancer patients and disrupts BM hematopoiesis and favors immunosuppression and tumor progression." (PMID 34552585, 2021). "Consistently, in this study, the expression of COL1A1 in tumor tissues was distinctly higher compared with normal tissues." (PMID 33490271, 2021).
tumor (continued). "Through a systems medicine approach, it was determined that hub biomolecules, AR, GATA2, miR-124, TOR1AIP1, ESR1, EGFR, STAT1, miR-192, GATA3, COL1A1, in tumor microenvironment generic network." (PMID 33907495, 2021). "We also show that decreases in HAPLN1 proteins are associated with increased COL1A1 protein levels in CRC epithelial cells after TGF-β challenge and control tumor growth." (PMID 34966673, 2021). "In fact, we found that the extent of tumor growth suppression by BMP1 correlated linearly with the endogenous COL1A1 expression levels." (PMID 33879793, 2021). "Mut COL1A1 cells showed small but significant increases in their in vitro proliferation rate, as well as primary tumor weight and lung and liver metastasis load when orthotopically implanted in comparison to WT COL1A1 cells." (PMID 33879793, 2021). "We chose Collagen Type 1 Alpha 1 (COL1A1) as the most relevant prognostic marker due to its high number of pathway connections and over expression in the tumor microenvironment compared to the other 12 genes." (PMID 33062455, 2020). "In our NCKU-OrCA-40TN cohort, we noticed that five collagen subunits are upregulated genes in the tumor tissues compared to that in the normal counterparts, including COL1A1 (3.5×), COL4A1 (2.1×), COL4A2 (3.3×), COL4A5 (5.6×), and COL4A6 (9.2×)." (PMID 32244515, 2020). "In our study, to our surprise, we found that some ligands and receptors were highly expressed in both tumor cells and T cells, such as collagen and integrin family genes, such as COL1A1 and ITGB1." (PMID 32549766, 2020). "Using genome arrays, we ultimately identified COL1A1 as a relevant marker due to high expression in tumor samples and interconnectedness with other hub genes." (PMID 33062455, 2020). "The genes COL11A1 and COL1A1 are upregulated by miRNAs across five tumor entities (BRCA, LUAD, STAD, HNSC, and LUSC) and zebrafish samples (4, 7, and 14 dpi)." (PMID 33362851, 2020). "Based on the results of sequencing and bioinformatics analysis, MMP13 and COL1A1 were reported to contribute to the occurrence and development of tumor, especially the metastasis of tumor." (PMID 33014334, 2020). "To confirm this finding, we assessed COL1A1 expression, the most abundant molecule of the collagen family, in tumor tissues from CRC patients and colon tissues from healthy controls using an existing dataset (GSE128449)." (PMID 32171282, 2020). "Overall, these results confirm the concurrent gene upregulation of LOX, COL1A1, senescent cells, and CAFs markers in tumor tissues and in particular in those with BRAF-like signaling." (PMID 31906302, 2020). "Principal component analysis and random forest analysis were employed to further screen for six hub genes, including ISLR, COL1A2, CDH11, SPARC, COL3A1, and COL1A1, which exhibited a good ability to differentiate between tumor and normal samples." (PMID 32612640, 2020). "In this context, we validated the candidate hub gene COL1A1 which was regulated by autophagy and affected the drug sensitivity of tumour cells." (PMID 32319226, 2020). "Among them, the expression of COL1A1, COL10A1 and COL11A1 was particularly higher, and that of COL4A4, COL6A5 and COL14A1 was especially lower in tumor tissues, indicating their possible roles as diagnostic markers for ESCC." (PMID 31598423, 2019). "We also demonstrated that relative to the non-tumor tissues, COL1A1 protein expression was over-expressed in the HCC samples in a stage-dependent manner." (PMID 31181620, 2019). "COL1A1 expression profile in tumor and normal tissue samples was evaluated as well as the role and molecular mechanism of altered COL1A1 expression in the metastasis and stemness of HCC." (PMID 31181620, 2019). "COL1A1, a major component of collagen type I, serves a key role in the tumor cell adhesion and invasion." (PMID 30568862, 2018).
tumor (continued). "Collagen 1A1 (COL1A1) belongs to the collagen family, members of which are major components of the tumor-stromal environment with important roles in cancer cell behavior." (PMID 30237810, 2018). "The mechanistic study revealed that overexpressed COL1A1 promotes tumor metastasis by regulating the Wnt pathway." (PMID 30568862, 2018). "COL1A1 plays an important role in cancer, since tumor cells that express COL1A1 are able to dissociate from their surrounding stromal components, which is essential for tumor growth." (PMID 29740539, 2018). "Changes in several ECM components known to promote growth of tumour cells, such as the collagens COL1A1, COL1A2, and the MMP2 metalloprotease were also evident in XRCC1 KD cells, again reflecting an activated fibroblast phenotype." (PMID 29568385, 2018). "Increased extracellular levels of COL1A1 promote tumor cell invasiveness in culture and metastasis in animal models." (PMID 30237810, 2018). "COL1A1 and FN1 are individual ECM genes and have been reported to be associated with tumor invasion and metastasis." (PMID 30237810, 2018). "The presence of a common breakpoint clearly shows that the two genetically distinct subclones originated from a founder tumor cell in which a COL1A1-PDGFB fusion event occurred." (PMID 28977029, 2017). "Unlike the previous tumors, the tumor observed in 2010 showed an irregular shape with unclear boundaries between the tumor mass and normal tissue, while the COL1A1-PDGFB fusion was sustained." (PMID 28977029, 2017). "Although the difference in methylation between grouped normal and tumour samples was insignificant, pairwise comparison showed significant hypermethylation of COL1A1 promoter in NSCLC (p = 0.035, Wilcoxon test, N = 26 pairs)." (PMID 28258342, 2017). "We found that the L1CAM, TSPAN3 and SERPINA3 gene expression were significantly up-regulated in M than Wt sporadic tumor samples, whereas COL1A1 and MAT2A mRNA showed similar levels in both groups." (PMID 28418912, 2017). "Our comparative qPCR analysis showed abundant COL1A1 overexpression in tumours (median RQ = 975.4, IQR 389.9–3172.7, N = 132) when compared to adjacent normal tissues (69.4, 29.8–235.6, N = 119, Mann–Whitney test, p < 1 × 10−4)." (PMID 28258342, 2017). "Collectively, these results suggest that COL1A1 plays a pivotal role in formation of rigid tumor environments and thereby reduces the efficacy of chemotherapeutics in HCC spheroids." (PMID 28423507, 2017). "COL1A1 codes a protein associated with platelet-derived growth factor (PDGF) signaling pathway, which helps in the maintenance of tumor stromal and angiogenesis facilitation in metastasis." (PMID 27806706, 2016). "Results from this cytokine panel led us to look closer at different immune and stromal cell populations and their response to COX-2 inhibition in PyMT/Col1a1 and wild-type (WT) tumor microenvironments." (PMID 27000374, 2016). "Reverse transcription polymerase chain reaction (RT-PCR) of the tumor tissue revealed the presence of a COL1A1-PDGFB fusion gene." (PMID 26932148, 2016). "Collagen deposition in both PyMT and PyMT/Col1a1 tumor microenvironments was diminished with celecoxib; however, normal mammary glands were not affected by COX-2 inhibition." (PMID 27000374, 2016). "Our cytokine array data revealed elevation of several cytokines and growth factors associated with tumor cell proliferation and inflammatory response modulation in the PyMT/Col1a1 tumor microenvironment." (PMID 27000374, 2016). "The level of COL1A1 expression was higher in the muscular and serosa invaded tumors, while NCAM1 expression tended to be negatively associated with tumor invasion." (PMID 25860484, 2015). "Increased extracellular levels of Col1a1 have been shown to promote tumor cell invasiveness in culture and metastasis in animal models." (PMID 25090092, 2014). "Among 48 pairs of surgical specimens, 13 (27.1%) showed decreased COL1A1 mRNA expression in tumor sites." (PMID 24552139, 2014).